CD4 (CD4 molecule)
Diseases named in the same sentence as CD4 in open-access papers (continued):
Sharing a sentence is not in itself a finding about the gene and the disease.
rectal cancer (continued). "A TCR specific to the PIK3CAE545K, restricted by HLA-DRB1*04:01, was also identified following IVS of memory CD4 + PBL from another patient, with rectal cancer." (PMID 41410746, 2025). "Treatment that decreases Tregs and increases the expression of CD44 in CD4+ and CD8+ T cells, is able to suppress liver metastases and improve the overall survival rate in rectal cancer." (PMID 37709489, 2023). "The activity of CD8+ T cells in anti-tumor response is also strongly influenced by CD4+ T cells, that have also been found increased after CRT in rectal cancer biopsies." (PMID 37958298, 2023). "(C)RT of rectal cancer was shown to induce infiltration of CD8+ and CD4+ T cells, DCs as well as IFN-γ upregulation." (PMID 37958298, 2023). "Higher CD4+/CD8+ ratios of peripheral blood were still favorable for the prognosis of radiotherapy and regular treatment for rectal cancer patients based on our combined institutional peripheral blood data from 2018 through the March of 2021." (PMID 35534879, 2022). "This study showed favorable CD4+/CD8+ ratios and unfavorable CD8+ T cell component in predicting the response of preoperative RT for rectal cancer." (PMID 35534879, 2022). "The present study shows that immunonutiriton prior to surgery provides similar CD4 and CD8 T cell counts and FOXp3 levels compared to standard nutrition in locally advanced rectal cancer patients." (PMID 36326418, 2022). "IRF3 expression in patients with rectal cancer was negatively correlated with the infiltration level of CD8+ T cells, and positively correlated with the infiltration level of CD4+ T cells." (PMID 34488791, 2021). "In rectal cancer, CBX6 expression was positively correlated with the infiltration of CD4+ T cells, macrophages, and dendritic cells." (PMID 33014884, 2020). "The expression of CBX1 was in connection with the infiltration of CD4+ T cells, neutrophils, B cells, CD8+ T cells, macrophages, and dendritic cells in colon and rectal cancers." (PMID 33014884, 2020). "A high density of CD4+ and CD8+ tumor-infiltrating lymphocytes (TILs) within rectal-cancer tissue have shown better prognosis." (PMID 33442477, 2020). "In this study, we found that the density of CD4(+) and CD8(+) T cells in biopsy samples of rectal cancer showed a strong correlation with tumor response to CRT, indicating that tumors attracting T cells are more liable to respond to CRT." (PMID 21575175, 2011). "Moreover, a statistically significant correlation between better response to neoadjuvant therapy and increased CD4+ and CD8+ T-cell infiltration in pretreatment rectal cancer biopsies was demonstrated." (PMID 37232754, 2023). "The results showed that the low expression of GAS1 was negatively correlated with the distribution of CD4+ T cells, CD8+ T cells, macrophages, myeloid dendritic cells (DCs), and neutrophils in both colon and rectal cancer, but positively correlated with B cells." (PMID 33397428, 2021). "Our approach was to analyze whether CD4+ or CD8+ apoptosis and necrosis have a prognostic impact on tumor progression and metastasis in a prospective study of 87 homogenous treated rectal cancer patients." (PMID 27340400, 2016). "In rectal cancer, the expression level of ABCA5 was positively correlated with the infiltration level of B cells and CD8+ T cells, while it was not significantly different from the infiltration level of CD4+ T cells, macrophages, and neutrophils." (PMID 35783152, 2022).
relapsing-remitting MS (38 papers, 2009 to 2025). "In a previous study, we found a differentially methylation region (DMR) at MHC HLA-DRB1 that was associated within relapsing-remitting MS (RRMS) patients in CD4+ T cells." (PMID 28729889, 2017). "Disease activity in relapsing-remitting MS and in patients with clinically isolated syndromes is associated with an increased percentage of circulating CD4+CD26+ T cells." (PMID 22701554, 2012). "We investigated whether the CD4+CD28null T cell percentage is associated with a worse clinical disease course in 176 patients with relapsing-remitting MS (RRMS)." (PMID 28979263, 2017). "In the current study, we analyzed a group of patients suffering from relapsing-remitting MS who received in our center an experimental therapy consisting of CD4+CD25highCD127−FoxP3+ regulatory T cells." (PMID 37627928, 2023). "Individuals suffering from relapsing-remitting MS, in most of the studies, have decreased numbers of CD4+CD25+ Tregs and increased frequencies of Th1-like (CD4+CD25highCD45RA−CD127−Foxp3+) Tregs in their blood." (PMID 36140240, 2022). "In particular, the inhibitory effect of dopamine, norepinephrine, and 5-HT was shown on Th17-cytokines production by activated CD4+ T-cells in patients with relapsing-remitting MS and in healthy subjects." (PMID 36189272, 2022). "We have recently found that CD28 stimulation induces the expression of Th17 related cytokines in CD4+ T cells from HD, relapsing-remitting MS (RRMS) and T1D patients." (PMID 33178223, 2020). "Transfer of enriched CD4+ T cells from E-selectin tolerized mice limited disability in the passive SJL model of relapsing remitting MS." (PMID 31507371, 2019). "CX3CR1+CD4+ T cells were enriched in cerebrospinal fluid of relapsing-remitting MS patients and CX3CR1 appears critical for the development of CD8 memory T cells." (PMID 30386211, 2018). "Characteristics of relapsing-remitting MS cases and controls, and count of CD4+ and CD8+ T cell samples included in analyses." (PMID 30379917, 2018). "Using Affymetrix Human Transcriptome Arrays (HTA 2.0), we performed a transcriptome profiling analysis of CD4+ cells obtained from the peripheral blood of patients with highly active relapsing-remitting multiple sclerosis." (PMID 28155899, 2017). "Decrease in the number of CD4+Foxp3+ T cells as well as the expression level of Foxp3 is becoming an important characteristic of relapsing-remitting MS and other lymphoproliferative autoimmune disorders." (PMID 28367355, 2017). "Overexpressed IRF4 in naive CD4+ T cells derived from relapsing remitting multiple sclerosis patients significantly increased their ability to secrete IL-17A, IL-17F, IL-21, and IL-22." (PMID 28808358, 2017). "We report here that IL-1RI expression is significantly increased in both naive and memory CD4+ T cells derived from relapsing-remitting multiple sclerosis (RR MS) patients in comparison to healthy controls." (PMID 27965670, 2016). "Lesions in relapsing-remitting MS patients arise from a complex interplay of both CD4+ and CD8+ T cells, with B cells and innate immune cells playing critical roles in orchestrating T cell responses." (PMID 26339480, 2015). "Possible involvement in the development and progression of SCC (Squamous Cell Lung Carcinoma Tissues). miR-193a is strongly upregulated in CD4+ lymphocytes of relapsing-remitting multiple sclerosis patients." (PMID 25594007, 2014). "Expression of HLA-E was generally low, but significantly increased on CD4+ cells from primary progressive MS patients when compared with healthy controls (p<0.005) and relapsing remitting MS patients (p<0.031)." (PMID 23049954, 2012). "It has been shown that there is a significant decrease in the number of CD4+Foxp3+ T cells as well as the expression level of Foxp3 in relapsing-remitting MS and other lymphoproliferative autoimmune disorders." (PMID 23284794, 2012).
relapsing-remitting MS (continued). "Moreover, an inverse correlation has been observed between CD3-CD8+ NK cells and relapses in patients with relapsing-remitting multiple sclerosis, attributed to the suppressive regulatory effect of these NK cells on CD4 T cells." (PMID 41425544, 2025). "(2021) showed the inhibitory effect of fluoxetine on IL-17, IFN-γ, and GM-CSF production by anti-CD3/CD28-activated CD4+ T-cells in patients with relapsing-remitting MS and healthy subjects, which confirms the anti-inflammatory effect of fluoxetine on Th17-cells in MS." (PMID 36189272, 2022). "EAE, a rodent model of relapsing/remitting MS, is a CD4+ T cell-mediated disease of the CNS." (PMID 26092157, 2015). "For example, the expression of TLR2, TLR4, and TLR9 on CD4+ and CD8+ T cells was significantly higher in patients with relapsing remitting MS (RRMS) than healthy individuals." (PMID 34790205, 2021). "We, and others, have used genome-wide DNA methylation technologies to assess differentially methylated regions (DMRs) of CD4+ and CD8+ T cells in relapsing-remitting multiple sclerosis (RRMS) patients compared to healthy controls." (PMID 28729889, 2017). "Patients with stable RRMS (relapsing-remitting multiple sclerosis) showed comparable levels, whereas active RRMS patients demonstrated elevated frequencies of CD4+NKG2D+ T cells in the periphery." (PMID 24282598, 2013). "Furthermore, fluoxetine decreased the production of IL‐1β, IL‐6, and IL‐17 by activated CD4+ and CD8+ T-cells, suggesting an anti-inflammatory effect of treatment with fluoxetine on Th17-immune response in relapsing-remitting MS patients with MDD." (PMID 36189272, 2022). "In untreated relapsing-remitting MS (RRMS), a similar level of EBI2 expression was found in patients and the healthy controls; however, there was significant variability in EBI2 receptor levels found in CD4+ and CD1 T cells in the MS patients’ samples." (PMID 33919387, 2021).
skin cancer (38 papers, 2011 to 2026). "Human clinical data has shown that increased CD4+ T cell infiltration is enhanced in spontaneously regressing NMSC, and in mice, the depletion of CD4+ T cells enhances susceptibility to radiation-induced skin tumors." (PMID 37175480, 2023). "In particular, the depletion of CD4+ lymphocytes is a well known predisposer for skin cancers." (PMID 23938065, 2013). "Considering the CD4+ T cell blood count and HIV viral load in plasma, a CD4+ T cell count < 350 cells/μL and an HIV load > 20 copies/mL were significantly associated with skin cancers (respectively, p = 0.019362 and p = 0.015742)." (PMID 41010651, 2025). "CD4+ Th2 cells were required and were sufficient downstream of thymic stromal lymphopoietin cytokine induction by calcipotriol to suppress skin cancer development." (PMID 39744942, 2025). "To determine the role of CD4+ T cells in mediating the efficacy of calcipotriol-plus–5-FU immunotherapy for skin cancer suppression in vivo, we studied the spontaneous chemical skin carcinogenesis model in mice." (PMID 39744942, 2025). "WT CD4+ T cell transfer reconstituted skin tumor protection in Tslptg TslprKO mice, as shown by delayed tumor development compared with Tslptg TslprKO mice that received TslprKO CD4+ T cells." (PMID 39744942, 2025). "Further, MF skin tumor T cells have significantly increased MHC-I expression compared to healthy CD4+ T cells." (PMID 38272918, 2024). "Studies have shown that CD4+ UVB-induced regulatory T-cells are involved in the inhibition of effector cells during the development of UV-induced immunotolerance of skin tumors." (PMID 34771569, 2021). "It even slightly increased the tumor incidence in wt/HPV8 mice, a finding that contradicts the tumor‐promotive role of CD4+ T cells in a HPV16 skin cancer model." (PMID 27932444, 2017). "In the current study, the transfer of ex vivo—expanded CD4+ T cells significantly delayed skin tumor growth." (PMID 28854279, 2017). "Although the transfer of activated whole spleen cells delayed skin tumor growth, the transfer of ex vivo—expanded CD4+ T cells and CD8+ T cells strongly inhibited tumor progression." (PMID 28854279, 2017). "The depletion of Tregs following irradiation and the transfer of ex vivo—expanded CD4+ T cells significantly inhibited skin tumor growth." (PMID 28854279, 2017). "By contrast, significant retardation of skin tumor growth was observed in mice reconstituted with CD4+ T cells." (PMID 28854279, 2017). "In general, the incidence of skin cancer is proportional to the level of immune suppression, as CD4 counts are significantly lower in OTR with SCC versus those patients without such malignancy." (PMID 23667456, 2013). "Specifically, UVR expanded peripheral blood CD4+ regulatory T cells (Tregs), which in turn led to greater Treg infiltration and immunosuppression in colorectal and skin cancer, and colorectal ICB-resistant tumors expressed unique pathways of ICB resistance due to systemic UVR." (PMID 41176313, 2025). "To determine whether Th2 polarization was required in TSLP-activated CD4+ T cell immunity against skin carcinogenesis, we examined skin tumor development in Il4ra–/– (Il4rKO) and Tslptg Il4rKO mice." (PMID 39744942, 2025). "Additionally, we observed high expression of Pdcd1 in skin tumors, highlighting the potential role of CD4+ T cells in checkpoint inhibitor immunotherapy." (PMID 40282557, 2025). "However, CD4+ T cell transfer into Tslptg Rag1KO reconstituted skin tumor protection in these animals." (PMID 39744942, 2025). "Future studies on this cytotoxic subset of CD4+ T cells during skin tumor progression may offer insights into novel therapeutic strategies and improve clinical outcomes." (PMID 40282557, 2025). "This suggests a potential role of this cytotoxic subset of CD4+ T cells in skin tumor progression." (PMID 40282557, 2025).
skin cancer (continued). "Combinations of antibodies against PD-1, 4-1BB and VISTA fulfil this brief by not only targeting positive and negative signaling pathways on CD8 cytotoxic T cells, but also impacting on CD4 effector T cells, NK cells, regulatory T cells and myeloid-derived suppressor cells within skin cancers." (PMID 34282763, 2021). "This study demonstrates that patients who have previously developed a cSCC have increased numbers of FOXP3+ CD4+ T cells, which may prove to be a useful marker of skin cancer in transplant recipients." (PMID 25250867, 2014). "Nevertheless, CD4KO mice are less prone to skin tumor formation, and it has been hypothesized that this is caused by lack of tumor-promoting CD4 T helper cells." (PMID 39905055, 2025). "The detection of CD4 T cells distinguished by KYNU expression suggests that gene expression changes resembling those seen in tumors may occur even in the photo-damaged adjacent skin of skin cancer patients, highlighting the importance of including such tissues as comparator samples." (PMID 38334658, 2024). "In a transgenic model of skin cancer induced by HPV 16 oncogenes, infiltrating CD4+ T cells detected in malignant lesions were predominantly reactive toward S. aureus antigens and not HPV oncogenes." (PMID 28854209, 2017). "The levels of Treg cells such as CD4+ and CD25+ have been shown to be increased in lung, pancreatic, breast, liver, and skin cancers." (PMID 29410961, 2017). "Consistently, we observed the co-localized expression of Cd4 and Ifng in skin tumors, but not in control skins." (PMID 40282557, 2025). "In contrast, Rag1KO mice that received CD4+ T cells did not gain protection against skin tumor development." (PMID 39744942, 2025). "Having shown that αβ‐T cells were decreased in skin tumors, we next addressed whether this applies to CD8+ or CD4+ T cell subsets." (PMID 32615027, 2020). "Therefore, we can conclude that the skin cancers in our series of PLWH were not solely linked to immune status, unlike the population of OTRs, whose risk of skin cancers correlates with a lower CD4+ T cell count." (PMID 41010651, 2025). "The drastic reduction of B cells (CD19+), from 48.44% at the start of treatment to 1.71% at the time of skin tumor diagnosis, demonstrated the potent targeting of Orelabrutinib in controlling MCL, while a significant increase in total T cell (CD3+) and helper T cell (CD4+) numbers was observed." (PMID 41398799, 2025). "Interestingly, there is no strong evidence correlating the extent of CD4 count decline or HIV viral load to the incidence of skin cancers." (PMID 39314575, 2024). "Moreover, Tregs comprise 8–20% of the CD4+ T cell population in normal adult skin, but they account for approximately 45% of CD4+ cells in the BCC TME, demonstrating a two-fold increase that mediates the immunosuppressed environment to favor skin cancer progression." (PMID 37173918, 2023). "In skin cancer, chemokines such as CCL-17 and CCL-18 secreted by stromal cells can recruit immunosuppressive regulatory T (Treg) cells to infiltrate in tumor islands, and overexpression of CCL-17 and its ligand CCR-4 can promote the aggregation of CD4-positive (CD4+) Treg, Th2 and Th17 cells." (PMID 36159822, 2022). "With respect to cutaneous immunity, the failure to repair damaged DNA leads to the generation of CD4+CD25+ regulatory T-cells and recruitment of MDSCs into the tumor microenvironment, both of which serve to limit host defenses directed at cells destined to become skin tumors." (PMID 34771569, 2021). "Because inflammation is a crucial factor in skin tumour development and EPI−/− skin has an abnormal number of DETCs and CD4+CD3+ lymphocytes, we examined whether the inflammatory response to short term TPA treatment was altered in skin with a defective epidermal barrier." (PMID 24843010, 2014).